CFAP61 (cilia and flagella associated protein 61)
Description:
Involved in sperm flagellum assembly. Plays an essential role in the formation of the radial spokes in flagellum axoneme (By similarity).
Synonyms: C20orf26; DKFZP434K156; dJ1002M8.3; CaM-IP3; SPGF84; dJ1178H5.4
Tractability: Small molecule: a structure with a bound ligand is known.
Gene: Protein-coding gene on chromosome 20 (20,052,514 to 20,360,703, forward strand). Ensembl gene ENSG00000089101.
Subcellular location: Cytoplasm, cytoskeleton, flagellum axoneme; Cytoplasm, cytoskeleton, cilium axoneme; Cell projection, cilium; Cytoplasm, cytoskeleton
Subcellular location (Human Protein Atlas): Cytosol; Principal piece; Nucleoplasm
Gene Ontology:
Biological process: flagellated sperm motility; sperm flagellum assembly; cilium movement; cilium organization
Cellular component: axoneme; sperm flagellum; motile cilium; radial spoke stalk; cilium; cytoskeleton
Genetic constraint (gnomAD): Loss-of-function variants: 87 observed, 116.5 expected, observed/expected ratio (o/e) 0.75, 90% interval 0.63 to 0.89. The upper end of that interval is the gene's LOEUF score, 0.89, which puts it in group 3 of 6, group 1 being the genes least tolerant of losing a copy. Missense variants: 1,290 observed, 1,389.6 expected, observed/expected ratio (o/e) 0.93, 90% interval 0.89 to 0.97. Synonymous variants: 489 observed, 523.01 expected, observed/expected ratio (o/e) 0.93, 90% interval 0.87 to 1.01.
Homologues: Orthologues: chimpanzee CFAP61 (99% identical), macaque CFAP61 (97% identical), dog CFAP61 (85% identical), rabbit CFAP61 (83% identical), pig CFAP61 (82% identical), rat Cfap61 (76% identical), mouse Cfap61 (75% identical), tropical clawed frog cfap61 (58% identical), zebrafish si:zfos-223e1.2 (21% identical), Drosophila melanogaster CG30275 (18% identical), Drosophila melanogaster CG30268 (18% identical).
Diseases named in the same sentence as CFAP61 in open-access papers:
CFAP61 is named in the same sentence as 6 diseases in open-access papers, as found by Europe PMC text mining. Sharing a sentence is not in itself a finding about the gene and the disease. The quoted sentences say what the papers report.
male infertility (5 papers, 2021 to 2025). The inability of the male to effect fertilization of an ovum after a specified period of unprotected intercourse. "Biallelic mutations in CFAP61 lead to morphological irregularities in flagella, resulting in male infertility." (PMID 40519260, 2025). "Altogether, our findings report that homozygous variants in CFAP61 are associated with MMAF and male infertility, demonstrating the essential role of this gene in normal sperm flagellum structure in humans." (PMID 35174165, 2021). "Moreover, Cfap61 knockout mice displayed multiple morphological and ultrastructural abnormalities, severely reduced sperm count and motility, and male infertility." (PMID 35174165, 2021). "Damaging mutations in genes encoding RS1 and RS2 components cause PCD, while mutations in genes encoding RS3 proteins, CFAP61, CFAP91, CFAP251, and LRRC23 result in male infertility but not PCD." (PMID 40886204, 2025). "Strikingly, in mice and humans, mutations in CFAP61, CFAP91, CFAP251, and LRRC23 cause male infertility but not primary ciliary dyskinesia or hydrocephalus, suggesting more differences in the RS3 structure and/or function between sperm flagellum and cilia in multiciliated cells." (PMID 40886204, 2025).
anxiety depression (1 paper, 2022). "In our study, CFAP61 was found to be significantly associated with non-anxiety depression and had been identified to play a vital role in primary cilia affecting cerebral cortical development and dysfunction." (PMID 35730328, 2022). "Examining significant genes that overlap between the current GWAS of non-anxiety depression and the depression studies revealed putative associations with PIEZO2 and CFAP61." (PMID 35730328, 2022). "CFAP61 gene identified by our GWAS is a remarkable finding for non-anxiety depression with respect to known biology and points to the potential value of other novel findings from this kind of research." (PMID 35730328, 2022).
COVID-19 (1 paper, 2025). A disease caused by infection with severe acute respiratory syndrome coronavirus 2. "The hypermethylated genes with the lowest p values for hospitalized COVID-19 patients at inclusion (T1) vs. at 6 weeks post-inclusion (T2) were PARP9, ABCA1, MX1, OAS1, ARID5B, and the hypomethylated genes included TMEM131, ROCK1, IFNGR1, CFAP61, VRK2, and C6orf138." (PMID 41227320, 2025).
depression (1 paper, 2022). "Several genes that are nearly adjacent to PIEZO2 and CFAP61 have been implicated in depression." (PMID 35730328, 2022). "To date, neither PIEZO2 nor CFAP61 has been reported to cause a phenotype related to depression." (PMID 35730328, 2022). "However, the role of CFAP61 in depression has not been well studied, and the role of CFAP61 in the brain or nervous system is also limited." (PMID 35730328, 2022).
infertile (1 paper, 2023). "For example, WES of infertile males without PCD symptoms identified mutations in CFAP251 and CFAP61." (PMID 38091523, 2023).
primary ciliary dyskinesia (1 paper, 2023). A rare, genetically heterogeneous, primarily respiratory disorder characterized by chronic upper and lower respiratory tract disease. "Previous studies have found that mutations in RSPH1 and CFAP61 cause disintegration of the sperm flagellar structure and primary ciliary dyskinesia." (PMID 37601242, 2023).